OCLN (occludin)
Diseases named in the same sentence as OCLN in open-access papers (continued):
Sharing a sentence is not in itself a finding about the gene and the disease.
tumor (continued). "For example, during the process of tumor-mediated angiogenesis, BM recruit healthy endothelial cells from surrounding brain parenchyma, but the vascularization process is disturbed by tumor-induced lack of transmembrane tight junction proteins occludin, claudin-1, and claudin-5." (PMID 28493907, 2017). "In our study, MCRS1 overexpression increased epithelial permeability and reduced both ZO-1 and Occludin expression, indicating that MCRS1 overexpression may abolish the functions of TJs and promote cellular invasion and tumor metastasis through the suppression of TJ molecules." (PMID 25373388, 2014). "A combination of western blotting and immunochemistry analysis also demonstrated that papaverine could downregulate claudin-5, occludin and F-actin expression by tumor microvessels, but not in normal brain tissue, suggesting that the tumor BBB opening was due to TJ dysfunction." (PMID 33198244, 2020). "It has been suggested that inhibition of occludin may act on TJs directly or indirectly to bind with factors that regulate cell proliferation, differentiation and cell cycle, receiving and imparting PKC and Rho protein etc. molecular signaling, regulating tumor cell survival." (PMID 24245968, 2013).
cancer (94 papers, 2011 to 2026). A tumor composed of atypical neoplastic, often pleomorphic cells that invade other tissues. "The loss of occludin can disrupt tight junction integrity and lead to the loss of cohesion in cellular structures, facilitating the invasion and metastasis of cancer cells." (PMID 39200479, 2024). "EMT-associated proteins, E-cadherin and Occludin, act as epithelial markers and are believed to be inhibitors of invasion and growth of epithelial origin cancer types." (PMID 37490511, 2023). "Loss of occludin and E-cadherin is associated with cell motility and a poor clinical outcome in human cancers." (PMID 35883447, 2022). "Genetic alteration and morphological changes are modulated during cancer metastasis, such as loss of epithelial cell identity (e.g., occludin and EpCAM) and acquisition of mesenchymal features (e.g., vimentin and TWIST1)." (PMID 24039787, 2013). "However, in cancer cells, high levels of Occludin are associated with reduced invasiveness and motility." (PMID 39592661, 2024). "Clusters of TCF4 binding sites are present in promoters of the CLDN2, CLDN4, CLDN7, and OCLN genes, and these genes could thus be upregulated in cancers with APC mutations." (PMID 37998722, 2023). "Moreover, about 90% of deaths associated with cancers occur due to metastasis, which overcomes tight junction proteins such as claudin and occludin." (PMID 42040792, 2022). "Moreover, they can protect the tight junction (Occludin, ZO-1) between colonic epithelial cells, prevent DNA damage, and reduce cancer risk." (PMID 33776762, 2021). "Occludin (OCLN) is an important tight junction protein and has been reported to be abnormally expressed in the development of malignant tumors." (PMID 37809090, 2023). "The CpG island hypermethylation of occludin promoter enhances the tumorigenic, invasive, and metastatic properties of cancer cells." (PMID 36672179, 2023). "The Cancer Genome Atlas database and Human Protein Atlas database were used to analyze the expression of OCLN in KIRC." (PMID 37809090, 2023). "As a driver of EMT, ZEB1 downregulates canonical epithelial genes (e.g., E-cadherin, occludin) and upregulates mesenchymal markers (e.g., vimentin, fibronectin) in different types of carcinomas." (PMID 37870961, 2023). "To-date, much research has focused on the role of deregulated claudin and occludin proteins in cancer development." (PMID 36484008, 2022). "We observed the elevated expression of fibronectin, vimentin, MMP-9, and N-cadherin with a parallel reduction in the levels of occludin and E-cadherin in the untreated cells indicating that the tested cancer cells present mesenchymal-like characteristics." (PMID 35883447, 2022). "During the EMT process, cancer cells withdraw the epithelial markers (such as occludin and E-cadherin) and express mesenchymal markers (fibronectin, vimentin, and N-cadherin), which make the cancer cells mobile and disease aggressive." (PMID 35883447, 2022). "OCLN’s protein expression can influence the development of several cancer types, including ovarian cancer, lung adenocarcinoma, and breast cancer metastasis." (PMID 34142021, 2021). "The incorporation of Ti nanoparticles to influence cancer resistance by the modulation of OCLN protein has excellent potential for future studies." (PMID 34142021, 2021). "The tight junction structure is one of the inevitable barrier for cancer cells to enable metastasis, whereas OCLN (Occludin) is one of the early identified tight junction proteins." (PMID 33450402, 2020). "Recent evidences suggest that Slug participates in epithelial-mesenchymal transition (EMT) during embryonic development and cancer metastasis by suppressing the expressions of its downstream target genes like E-cadherin, occludin, claudin-1, and integrin α3." (PMID 30612578, 2019). "The PMCs located near the invaded cancer cells displayed low expression of connexin 43, E-cadherin, occludin, and desmoglein, as well as expressed SA-β-Gal, a marker of senescence." (PMID 31110245, 2019).
cancer (continued). "Recent evidence suggest that Slug participates in EMT in embryonic development and cancer metastasis by inhibiting the expression of their downstream target genes such as E-cadherin and occludin." (PMID 31060565, 2019). "Slug, a well-known zinc finger transcriptional repressor, has been reported to participate in epithelial–mesenchymal transition (EMT) and cancer metastasis by suppressing its downstream target genes (such as E-cadherin, occludin, claudin 1, and integrin α3)." (PMID 31847356, 2019). "The study showed an apical distribution of CEA in well-differentiated cancer tissue, which also had a high expression of occludin." (PMID 30140423, 2018). "While only 4 cases showed occludin immunoreactivity (8.9%) and all of them show positivity less than 25% of cancer cells." (PMID 27398181, 2016). "Only 4 cases showed occludin immunoreactivity (8.9%) and all of them show positivity less than 25% of cancer cells." (PMID 27398181, 2016). "This stabilization of E-cadherin and occludin expression by Daxx prevents cell dissemination, and thus suppresses cancer cell invasion and metastasis during hypoxia." (PMID 28004751, 2016). "This EMT program displayed a significant reduction of E-cadherin and occludin expression, and a marked increase of N-cadherin, vimentin, and nuclear β-catenin expression, resulting in cancer cells evolving into a highly invasive and mesenchymal phenotype." (PMID 25645291, 2015). "It usually binds to actin cytoplasmic filaments and another tight junction protein- occludin that are down-regulated in highly invasive cancer cells." (PMID 25200553, 2014). "Consistent with this idea, several previous studies have revealed that the expression of occludin and claudins are altered in a number of types of cancer." (PMID 24348776, 2014). "Expression levels of the TJ proteins, claudin, zo-1 and occludin, are increased, resulting in the inhibition of invasion and metastasis by cancer cells." (PMID 23715597, 2013). "Downregulation of occludin can reduce cancer sensitivity to apoptogenic factors by modulating apoptosis-associated genes." (PMID 23919753, 2013). "Typically, overexpression of TJ proteins (claudin, zo-1 and occludin) and TJ-related proteins (β-catenin) is observed in cancer cells." (PMID 23715597, 2013). "Occludin appears to be associated with disease progression in HGSC and may predict chemotherapy response in this cancer, though this should be validated in other series." (PMID 38141113, 2024). "As most human cancers are of epithelial origin (carcinoma), the transcriptional downregulation of adherent/tight junction proteins (e.g., E-cadherin, Claudin and Occludin) with the concomitant gain of adhesive and migratory phenotypes has been extensively studied." (PMID 37892112, 2023). "By TIMER database mining, the expression level of OCLN was obtained from a pan-cancer perspective." (PMID 37809090, 2023). "The expression of OCLN was down-regulated in eight cancer types including KIRC." (PMID 37809090, 2023). "Claudins, Occludin and zonula occludens (ZO) are mostly studied in cancer researches." (PMID 33613746, 2021). "Interestingly, spheroid cancer cells with an increased OCLN expression developed cisplatin resistance, showing the importance of this gene in MDR." (PMID 34142021, 2021). "However, in the MARVEL family, occludin, tricellulin, and marvelD3, little is known about changes in their expression during cancer progression." (PMID 34338154, 2021). "The opposite role of Occludin in different cancer was also reported 28-30." (PMID 33613746, 2021). "With protein expression, cytokine activation, and penetration analysis, the ASM showed higher expression of cancer markers associated with proliferation (p-AKT, p-Erk), tight junction formation (Fibronectin, ZO-1, Occludin), and epithelial cell identity (E-cadherin) in HCC cells." (PMID 34443536, 2021).
cancer (continued). "Interestingly, we found that Daxx expression generally correlated with expressions of E-cadherin and occludin, and inversely correlated with cell invasiveness, suggesting a potential role of Daxx in regulating cancer cell invasiveness." (PMID 28004751, 2016). "The downregulation or upregulation of claudins and occludin might have a role in cancer development." (PMID 27398181, 2016). "Thus, identifying factors that regulate the metastasis-promoting actions of the Slug-E-cadherin/occludin axis would be important for the development of therapeutic strategies to target cancer metastasis." (PMID 28004751, 2016). "We also considered the analysis of recurrence of cancer, and we found that the level of gene expression in the normal tissue was associated with recurrence for many genes: FOXC2, CDC20, OCLN and SERPINB2 (p = 0.0067, p = 0.0067, p = 0.048 and p = 0.0352 respectively)." (PMID 25575813, 2015). "In addition, occludin decreases cellular invasiveness and motility, thus its downregulation can potentially favor cancer metastasis." (PMID 23919753, 2013). "Importantly, another tight junction gene, OCLN, occludin, was shown to be closely involved in resistance to apoptogenes as cisplatin and gamma irradiation, and re-expression of OCLN sensitized cancer cells to these agents." (PMID 22905093, 2012). "Although lesions with poorer differentiation showed reduced expression (dot pattern) of Zo-1 and occludin, the barrier function of tight junction may be essential for epithelial cells including carcinoma to maintain the microenvironment." (PMID 21473743, 2011). "Additionally, down-regulation of occludin has also been shown to lead to elevated levels of progression and metastatic potential in cancers, and it also might be the reason for activating of EMT and a consequent down-regulation of adhesion associated proteins." (PMID 27096955, 2016). "Analysis of human cancer datasets confirms that elevated WNT gene expression is associated with high levels of CUX1 and GLIS1 and correlates with genes of the epithelial-to-mesenchymal transition (EMT) signature: VIM, SNAI1 and TWIST1 are elevated whereas CDH1 and OCLN are decreased." (PMID 25217618, 2014). "A more mesenchymal-like morphology, down-regulation of the epithelial marker Occludin, and increased expression of the mesenchymal markers α-SMA and Vimentin were also seen in cancer cells." (PMID 38175202, 2024). "Cancers with MSI were characterized by downregulation of claudin 1, claudin 3, and claudin 4 and upregulation of claudin 7 and occludin." (PMID 37998722, 2023). "MMP1 facilitates cancer cell transit across the endothelium of the brain and increases BBB permeability by degrading the inter-endothelial junctions (claudin-5 and occludin)." (PMID 37190188, 2023). "As EMT is a common process that has been postulated to be responsible for carcinoma cell metastasis, the effect of the BCSC secretome on the expression of epithelial markers (CDH1, TJP1 and OCLN) and mesenchymal markers (Snail, FN1, MMP2 and VIM) was assessed." (PMID 36915147, 2023). "This was suggested to occur from cancer cell-derived VEGF-stimulated phosphorylation and ubiquitination of occludin, therefore impacting the tight junction-regulating function of occludin." (PMID 33659922, 2021). "Cancer cell migration and invasion rely on EMT, during which epithelial markers (E-cadherin, ZO-1, and Occludin) are downregulated, whereas mesenchymal markers (vimentin, N-cadherin, and Fibronectin) are upregulated." (PMID 33757532, 2021). "For instance, exosomal miR-25-3p derived from cancer cells stimulates vascular permeability and angiogenesis through modulating the expression of VEGFR2, ZO-1, occludin and Claudin5 in endothelial cells." (PMID 32364530, 2020). "It is of note that de-novo expression or upregulation of occludin was also found in cancers that are derived from occludin negative cell types." (PMID 40173205, 2025).
cancer (continued). "TRA16-positive cancer cells exhibited increased outgoing signaling via COMPLEMENT, VEGF, EPHA, PARs, GDF, BRADYKININ, BAG, MHC-I, OCLN, and CDH pathways, while receiving more incoming signaling through MK, THBS, GDF, LIGHT, OCLN, CDH, and NRG pathways." (PMID 40432923, 2025). "Furthermore, Twist1 expression positively correlates with EMT genes (CDH1, OCLN, TJP1, CDH2, FN1, SNAI1 and VIM) in various cancers." (PMID 32337580, 2020). "Furthermore, immunofluorescence analysis confirmed an overall strongly reduced intensity of occludin and JAM-A levels between cancer cells, suggesting reduced tight-junction mediated cell-cell adhesion." (PMID 29731961, 2018). "The preservation of the intestinal mucosal barrier in the EIN + L-OHP group, as indicated by higher levels of ZO-1 and Occludin, also suggests that EIN may help protect against chemotherapy-induced gut toxicity, a major complication that can limit treatment intensity in cancer patients." (PMID 41387645, 2025). "With regard to the movement of cancer cells across the endothelial cell barrier during metastasis, HGF facilitates cancer cell–endothelial cell contact through phosphorylation of focal adhesion kinase (FAK) and reduces occludin, the primary protein in endothelial tight junctions." (PMID 33271944, 2020). "This down-regulation was due to transcriptional or post-transcriptional deregulation, given that these cancers did not possess deep deletions or mutations in claudin genes, CLDN3, CLDN4 or CLDN7, and only 5% of claudin-low cases had deep deletions in the occludin gene OCLN." (PMID 37504297, 2023). "Upregulation was observed in many genes, including CAV2, FGFBP1, KRT19, MST1R, OCLN, and RGS2, which play important roles in the negative regulation of EMT and metastasis phenotypes in many cancers." (PMID 37298519, 2023). "The expression of CLIC2 and tight junction proteins is upregulated in non-cancer, compared with cancer cells, and CLIC2 regulates the formation of tight junction proteins such as claudin 1, claudin 5, zonula occludens-1, and occludin." (PMID 35205604, 2022).
inflammation (14 papers, 2015 to 2025). Aberrant reaction of the microcirculation characterized by movement of fluid and leukocytes from the blood into extravascular tissues. "Low occludin levels are associated with the disruption of TJs in the jejunum and consequently with the passive loss of solutes and the osmotically driven flow of water into the intestine, resulting in diarrhea, one of the main signs of intestinal inflammation." (PMID 31297194, 2019). "Loss of ZO-1 and OCLN from cerebral vascular endothelium was also observed during CNS inflammation." (PMID 26586924, 2015). "Knockdown of ZO-1, occludin, or MUC2 in mice impairs intestinal mucosal repair and increases the risk of intestinal inflammation." (PMID 39717557, 2024). "Still, studies have also found that both declines of tight junction proteins (like ZO-1, claudin-1, occludin) and increasing permeability (leaky gut) appear forward to severe gut inflammation." (PMID 36101343, 2022). "Oral administration of micronized PGA improved the DAI score and resulted in macroscopic amelioration of intestinal inflammation, as shown by the increased expression of tight junction proteins (ZO-1 and occludin) in the colonic mucosa and lower histological damage score." (PMID 36009057, 2022). "Additionally to colonic inflammation, CB0313.1 also reduced the colon permeability by upregulating the tight junction (TJ) proteins (claudin-1 and occludin) and contributed to a decreased circulating endotoxin level." (PMID 27123997, 2016).
bacterial infection (13 papers, 2014 to 2026). "By reducing the uptake of toxins during pathogenic bacterial infections, Occludin contributes to the tightness of intestinal epithelial cells." (PMID 40012772, 2025). "Vitamin D can also increase the expression of E-cadherin and occludin proteins in vaginal tissues, maintain the integrity of the vaginal epithelium, increase the number of Lactobacillus, and reduce pathogenic bacterial infections." (PMID 37764381, 2023). "In addition to mucoprotein, Claudin-1, and Occludin proteins are the backbones that mainly constitute the tightly linked chains that reduce the uptake of toxins by the organism during pathogenic bacterial infections." (PMID 37138630, 2023). "An in vitro BBB model was constructed using a brain microvascular endothelial monolayer to examine the effects of bacterial infection on the expression of tight junction proteins (occludin, Claudin-5, ZO-1)." (PMID 41987901, 2026). "Bacterial infection dramatically decreased OCLN, CLDN-2, and ZO-1 gene expression in the ileum, but probiotic administration significantly boosted OCLN, ZO1, and CLDN -2 mRNA expression." (PMID 39203472, 2024). "We found that R. anatipestifer infection induced rapid SspA-mediated degradation of the TJ protein occludin and the BM protein collagen IV, which contributed to bacterial infection-induced BBB disruption." (PMID 38594770, 2024). "Although occludin was known to have decreased expression in cells and lungs of animals challenged with LPS, hypoxia, or bacterial infection, direct evidence from ARDS patients is limited." (PMID 39519146, 2024). "Following bacterial infection occludin undergoes hyperphosphorylation on Thr interestingly coincident with the raise in TEER observed at 6 hours." (PMID 24416363, 2014). "For example, cigarette smoke can reduce the levels of apical junction proteins, such as OCLN, ZO-1, and E-cad, which lead to disruption of the airway epithelial barrier and subsequently facilitate viral and bacterial infection, immune cell recruitment, and sustained inflammation of the lung tissue." (PMID 38413976, 2024). "Thus, the interactions of OCLN with ZO-1 and Claudin suggested that hEPLCs aggregations have a meaningful cellular functions such as ion transportation and defense mechanism from bacterial infection, as shown in the high expression in all TJ markers proteins." (PMID 28434170, 2017). "Our current study found that NLRP6 deficiency can maintain the expression of tight junction protein occludin in the lung during S. pneumoniae infection, indicating that NLRP6 plays a detrimental role in the epithelial barrier against bacterial infection." (PMID 35694317, 2022). "Likewise, bacterial infection significantly decreased OCLN, ZO1, and CLDN-2 gene expression in the jejunum, but probiotic supplementation boosted OCLN gene expression." (PMID 39203472, 2024). "These supported evidences were consistent with our presented data that ETEC K88 challenge could decrease the expression of ZO-1 and occludin in IPEC-J2 cells, and these down-regulations could be partially reversed by the application of L. salivarius prior to bacterial infection." (PMID 32774852, 2020).